ZC2HC1B (zinc finger C2HC-type containing 1B)
Synonyms: C6orf94; FAM164B; dJ468K18.5
Tractability: No criterion of Open Targets' tractability assessment is met for any kind of drug.
Gene: Protein-coding gene on chromosome 6 (143,864,436 to 143,938,343, forward strand). Ensembl gene ENSG00000118491.
Gene Ontology:
Molecular function: protein binding
Genetic constraint (gnomAD): Loss-of-function variants: 36 observed, 32.46 expected, observed/expected ratio (o/e) 1.11, 90% interval 0.85 to 1.46. The upper end of that interval is the gene's LOEUF score, 1.46, which puts it in group 6 of 6, group 1 being the genes least tolerant of losing a copy. Missense variants: 260 observed, 275.48 expected, observed/expected ratio (o/e) 0.94, 90% interval 0.85 to 1.05. Synonymous variants: 73 observed, 87.98 expected, observed/expected ratio (o/e) 0.83, 90% interval 0.69 to 1.01.
Homologues: Orthologues: chimpanzee ZC2HC1B (99% identical), pig ZC2HC1B (86% identical), dog ZC2HC1B (79% identical), guinea pig ZC2HC1B (78% identical), macaque ZC2HC1B (74% identical), rat Zc2hc1b (60% identical), mouse Zc2hc1b (59% identical), Caenorhabditis elegans zchc-1A (37% identical), Drosophila melanogaster CG30460 (31% identical), Drosophila melanogaster CG42675 (31% identical). Paralogues in human: ZC2HC1A (45% identical), ZNF474 (14% identical), ZNF475 (5% identical).